CD34 (CD34 molecule)
Diseases named in the same sentence as CD34 in open-access papers (continued):
Sharing a sentence is not in itself a finding about the gene and the disease.
heart disease (8 papers, 2013 to 2024). "The ambiguous results of multiple CD34+ cell-based therapeutic trials for patients with heart disease have halted the large-scale application of stem/progenitor cell treatment." (PMID 37147443, 2023). "Several studies presented the safety and efficacy of the CD34+ cells in the treatment of cardiac disease." (PMID 36249945, 2022). "There are several investigations over the last decade, which conclude encouraging data on the use of CD34+ cells in the treatment of cardiac disease; such as acute myocardial infarction, dilated cardiomyopathy and heart failure." (PMID 36249945, 2022). "It is thus obvious that CD133+/CD34+ BMMNCs stem cell therapy in heart disease is the one of choice that can be proposed to patients with minimal risk." (PMID 23983717, 2013). "CD34+ cells have demonstrated multipotent or even pluripotent capacities, making them good candidates for regenerative medicine, particularly for treating heart diseases." (PMID 35420389, 2022). "The frequency of CD34+CD38− cells observed in IHD and VHD samples was lower than the frequency reported in bone marrow samples from healthy individuals, showing that the hematopoietic stem cell compartment is also affected in heart disease patients." (PMID 28819363, 2017).
retinopathy (7 papers, 2014 to 2025). "The current study findings are consistent with our previous report showing safety and feasibility of intravitreal injection of autologous CD34+ BMSC as preliminary findings among study participants with vision loss from various different retinopathies." (PMID 39328826, 2025). "We obtained an investigational new drug clearance from the FDA to explore intravitreal injection of autologous CD34+ BMSCs for retinopathy." (PMID 39328826, 2025). "In a model of ROP involving oxidative stress and inflammation akin to conditions in aging, we had found that rats subjected to O2-induced retinopathy (OIR) presented a reduced number of CD34+ EPCs in their retinal vessels." (PMID 39767576, 2024). "Since both CD133+ and CD34+ cells have been successfully applied in cell therapies for retinopathy, CD133+CD34+ cells were directly applied in the present study." (PMID 35223834, 2022). "Thus, in a model of pathological angiogenesis, the absence of CD34 reduces epi-retinal vessel tuft formation, a process that contributes to vision impairment in human retinopathies." (PMID 27352134, 2016). "However, the absence of CD34 limits invasion of vessels into the vitreous and formation of epi-retinal tufts in the OIR model, which suggests that CD34 is involved in the pathological neovascularization causing vision loss in proliferative retinopathies." (PMID 27352134, 2016).
blood cancer (5 papers, 2016 to 2024). "According to OpenArray results, LINC01268, HOXB-AS3, MEG3 and TCL6 transcripts were selected since deregulated in CD34+ stem/progenitor cells; further lncRNAs have been selected for their associations with myeloid differentiation and deregulation in blood neoplasms." (PMID 34638230, 2021). "For each TF, we measured how well the DISCERN score of a gene can predict the differential binding of the TF in active enhancer regions (marked by H3K27Ac) within 15kbs of the transcription start site (TSS) of the gene and 5kb of the gene between blood cancer and normal cell lines (NB4 and CD34+)." (PMID 27145341, 2016).
breast (5 papers, 2010 to 2025). "Materials and Methods: We retrospectively evaluated microvessel density (MVD) by CD34 immunohistochemical (IHC) staining and hypoxia by IHC staining for Hypoxia-inducible factor 1α (HIF-1α), comparing right- and left-lung parenchyma in 53 lung NETs." (PMID 36233825, 2022).
kidney disease (5 papers, 2017 to 2023). "Local CD34+ capillaries decrease in mouse models of renal disease associated with the severity of glomerular and tubulointerstitial lesions." (PMID 35450390, 2022). "In this study, we examined the decrease in CD34+ renal capillaries associated with the progression of kidney disease using murine GLs and TILs models." (PMID 28870174, 2017). "In a future study, we will compare the loss of renal capillaries and decreased expression of CD34 as contributors to kidney disease progression." (PMID 28870174, 2017). "Therefore, CD34+ cell transplantation could apply renoprotective effects by improved angiogenesis and anti-inflammation capability and could be considered a new therapeutic tool for kidney disorders." (PMID 37138792, 2023).
CNS tumors (4 papers, 2015 to 2024). "In conclusion, we have shown that ERG is a novel and more reliable marker for endothelial cells within CNS tumors than CD31 and CD34 are, adding another tool to the arsenal for the evaluation of CNS tumors." (PMID 25881913, 2015). "However, a review of the literature indicates that very little has been done to assess the expression of ERG in CNS tumors, or to compare its reliability with that of other endothelial markers, such as CD31 and CD34." (PMID 25881913, 2015). "Furthermore, ERG dependably and intensely highlighted endothelial cells in CNS tumors, providing solid evidence that ERG is a more robust endothelial marker than CD31 and CD34 are." (PMID 25881913, 2015). "In our study we have demonstrated that unlike CD31 and CD34, ERG is exclusively expressed in endothelial cells within CNS tumors, lending support to the notion that ERG is a more specific marker for such cells." (PMID 25881913, 2015).
degenerative disease (4 papers, 2014 to 2021). "However, our established CD34+ cell expansion method provides an adequate number of stem cells for preclinical evaluations in various ischaemic and degenerative disease models 18,19,27." (PMID 24455991, 2014). "CD34+ cells may represent a potential cell target for therapeutic development in ALS and other neurodegenerative diseases." (PMID 31395804, 2019). "This growth pattern becomes even more evident using CD34 immunohistochemistry, as the class II CD34 epitope is not expressed in the adult normal mammalian central nervous system or any other neuroimmunological or neurodegenerative disease." (PMID 24858213, 2014).
infectious disease (4 papers, 2017 to 2024). A disorder directly resulting from the presence and activity of a microbial, viral, or parasitic agent in humans. "Cord-blood derived CD34 humanized mice are a widely used mouse model and have been utilized to study various infectious diseases in vivo." (PMID 33673566, 2021). "The analysis in CD34+ cells highlighted mechanisms related to SUMOylation of chromatin organization proteins, infectious disease, transcriptional activity of SMAD2/SMAD3 and cellular responses to stress." (PMID 31546608, 2019).
inflammation (4 papers, 2014 to 2021). Aberrant reaction of the microcirculation characterized by movement of fluid and leukocytes from the blood into extravascular tissues. "In this study, we have used a mouse model of lung inflammation induced with intranasal E. coli O55:B5 LPS (50 μL/mice) to study the role of CD34 in acute lung inflammation." (PMID 33632209, 2021). "Nevertheless, to our knowledge, only one report is available on the expression and role of CD34 in neutrophil recruitment during acute lung inflammation." (PMID 33632209, 2021). "However, only one report is available on the expression and role of CD34 in neutrophil recruitment during acute lung inflammation." (PMID 33632209, 2021). "Thus, it seems that elevated CD34+ levels in peripheral blood of CHB patients are related to persistent liver inflammation (detected by elevated levels IL-8 and IFN-α in CHB patients') and imbalance between injury and endogenous repair capabilities." (PMID 29461203, 2018). "Importantly, lung inflammation in fCB-CD34+ cell-treated mice was returned to normal levels as seen in basal mice at 52 h post-LPS challenge whereas PBS or CD34− cell-treated control mice exhibited persistent lung inflammation." (PMID 24558433, 2014). "In contrast, patients with poor response to ETV therapy had elevated levels of CD34+ HSPCs (5.9 ± 2.09) when compared to healthy controls, these elevated levels may be related to virological failure and persistent liver inflammation with mobilization of HSCs from the BM." (PMID 29461203, 2018).
bacterial infections (3 papers, 2016 to 2025). "For example, human CD34+ hematopoietic progenitor cells (HPCs) can also acquire mitochondria from BMSCs in response to acute bacterial infection, which causes bioenergetic changes that underpin emergency granulopoiesis." (PMID 38459012, 2024).
gastrointestinal tumors (3 papers, 2012 to 2024). "It was recently reported that immunohistochemistry for human herpesvirus-8 (HHV8), CD31, CD34, and D2-40 is useful for differentiating KS from other gastrointestinal tumors of similar appearance." (PMID 23227427, 2012).
metabolic disease (2 papers, 2013 to 2016). A congenital disorder (due to inherited enzyme abnormality) or acquired (due to failure of a metabolically important organ) disorder resulting from an abnormal metabolic process. "CD34+ cells were selected for the study as this population represents a good marker for metabolic disorders." (PMID 24223881, 2013).
gastrointestinal disease (1 paper, 2023). A disease that occurs in the gastrointestinal system, excluding the hepatobiliary system. "In addition, studies have found that interstitial cell of Cajal (ICC), which regulate the function of intestinal smooth muscle, are associated with more than a dozen gastrointestinal diseases, and ICC in rat intestinal tissue show CD34 immunoreactivity." (PMID 37051017, 2023). "CD34 is currently widely studied in a variety of gastrointestinal diseases." (PMID 37051017, 2023).
inflammatory myopathy (1 paper, 2013). "In a case of inflammatory myopathy, a lymphocytic infiltrate was observed around some NMSs, and CD34-positive intrafusal TCs appeared in varying number (generally few)." (PMID 23621814, 2013). "In pathological conditions, the number of CD34-positive TCs increased in residual NMSs between infiltrative musculoaponeurotic fibromatosis and varied in NMSs surrounded by lymphocytic infiltrate in inflammatory myopathy." (PMID 23621814, 2013).
CD34 also shares sentences with these, for which no sentence is quoted: acute myocardial infarction (31 papers); angiomyolipoma (8); dysplasia (6); B-cell acute lymphoblastic leukemia (5); genetic diseases (5); hematological cancers (4); malignant vascular tumor (4); paroxysmal nocturnal hemoglobinuria (4); combined immunodeficiency (3); desmoplastic melanoma (3); diffuse astrocytoma (3); ependymoma (3); germ cell tumor (3); left ventricular hypertrophy (3); neuroendocrine tumor (3); pheochromocytoma (3); retinitis pigmentosa (3); seminoma (3); spinal cord injury (3); undifferentiated carcinoma (3); acute erythroid leukemia (2); adrenal cortical tumors (2); adrenoleukodystrophy (2); anaplastic large cell lymphoma (2); angiokeratoma (2); bacteremia (2); bladder urothelial carcinoma (2); blue nevus (2); Buerger’s disease (2); cerebral palsy (2).
A further 242 diseases each share a sentence with CD34 in 2 papers or fewer.